MTPN (myotrophin)
Description:
Promotes dimerization of NF-kappa-B subunits and regulates NF-kappa-B transcription factor activity (By similarity). Plays a role in the regulation of the growth of actin filaments. Inhibits the activity of the F-actin-capping protein complex formed by the CAPZA1 and CAPZB heterodimer. Promotes growth of cardiomyocytes, but not cardiomyocyte proliferation. Promotes cardiac muscle hypertrophy.
Synonyms: GCDP; V-1
Tractability: Antibody: the Human Protein Atlas places it where antibodies can reach. PROTAC: ubiquitination databases record sites on it; its protein half-life has been measured.
Gene: Protein-coding gene on chromosome 7 (135,926,760 to 135,977,375, reverse strand). Ensembl gene ENSG00000105887.
Subcellular location: Cytoplasm; Nucleus; Cytoplasm, perinuclear region
Subcellular location (Human Protein Atlas): Cytosol; Plasma membrane
Gene Ontology:
Biological process: positive regulation of cardiac muscle hypertrophy; regulation of barbed-end actin filament capping; regulation of cell size; neuron differentiation; positive regulation of cell growth; positive regulation of macromolecule biosynthetic process; positive regulation of protein metabolic process; regulation of striated muscle tissue development; regulation of translation
Cellular component: F-actin capping protein complex; cytoplasm; cytosol; nucleus; perinuclear region of cytoplasm
Genetic constraint (gnomAD): Loss-of-function variants: 2 observed, 7.6 expected, observed/expected ratio (o/e) 0.26, 90% interval 0.11 to 0.83. That is too few expected variants to judge how well the gene tolerates losing a copy. Missense variants: 45 observed, 92.32 expected, observed/expected ratio (o/e) 0.49, 90% interval 0.38 to 0.62. Synonymous variants: 30 observed, 34.45 expected, observed/expected ratio (o/e) 0.87, 90% interval 0.65 to 1.18.
Homologues: Orthologues: chimpanzee MTPN (100% identical), macaque MTPN (100% identical), guinea pig MTPN (99% identical), mouse Mtpn (99% identical), pig MTPN (82% identical), rat Mtpn (81% identical), zebrafish mtpn (80% identical), dog MTPN (79% identical), tropical clawed frog mtpn (79% identical). Paralogues in human: ANKRD7 (37% identical).
Diseases named in the same sentence as MTPN in open-access papers:
MTPN is named in the same sentence as 25 diseases in open-access papers, as found by Europe PMC text mining. Sharing a sentence is not in itself a finding about the gene and the disease. The quoted sentences say what the papers report.
cardiac hypertrophy (7 papers, 2013 to 2022). "We investigated the role of variants of the microRNA-binding site in myotrophin in affecting its expression and any association with cardiac hypertrophy." (PMID 26274321, 2015). "It will be important to detect mechanisms underlying the effect of this variant or other variants in or near miRNA binding target site of myotrophin and true association between myotrophin polymorphisms with cardiac hypertrophy." (PMID 26274321, 2015). "Secondly, cardiac hypertrophy is known as a complex process affected by both genetic and environmental risk factors, and other variants in or near the myotrophin gene may exert important genetic effects on left ventricular hypertrophy risk." (PMID 26274321, 2015). "In summary, we report here that T allele of rs17168525 in the 3′-UTR of myotrophin might increase the risk of cardiac hypertrophy by interfering with let-7/miR-98 binding." (PMID 26274321, 2015). "miR-375-3p is also involved in cardiac remodelling as myotrophin, a direct target gene of miR-375-3p54, has been shown to initiate the transition from cardiac hypertrophy to heart failure." (PMID 35194110, 2022). "Of these, MTPN drives the growth of cardiomyocytes and promotes cardiac hypertrophy, whilst reduced CAPZA1 improves post-ischemic cardiac function." (PMID 31086124, 2019). "In vivo and in vitro studies have shown that myotrophin plays a vital role in the initiation of cardiac hypertrophy that transits to heart failure." (PMID 26274321, 2015). "Myotrophin, known as a myocardial hypertrophy-inducing factor, is responsible for the initiation of cardiac hypertrophy that transits to heart failure." (PMID 26274321, 2015). "In relation to MTPN, a protein related to cardiac hypertrophy, no significant relation with cancer has been reported to our knowledge." (PMID 23326553, 2013). "Therefore, decreasing platelet myotrophin activity in this study may be a protective response in the pathophysiology of CHF by limiting the NF-kB activity on cardiomyocytes, and the initiation process of myocardial hypertrophy in response to volume overload." (PMID 33256720, 2020).
diabetes (2 papers, 2018 to 2022). "Previously, it was observed that miR-375 has a role in diabetes, where its mechanism depends on controlling the expression of myotrophin (MTPN) and phosphoinositide-dependent protein kinase-1 (Pdk1) genes." (PMID 36874371, 2022). "MiR-375 has been reported to inhibit diabetes by targeting the expression of mRNA targets of miR-375 such as Gephyrin (GPHN), Insulin induced gene 2 (INSIG2), Myotrophin (MTPN) and Eukaryotic translation elongation factor 1 (Eef1e1)." (PMID 30379973, 2018).
glioma (2 papers, 2019 to 2021). A benign or malignant brain and spinal cord tumor that arises from glial cells (astrocytes, oligodendrocytes, ependymal cells). "We also collected some clinical specimens to verify the expression of HSPA5 and MTPN in glioma and normal brain tissue." (PMID 34026352, 2021). "qRT-PCR and Immunohistochemistry assay indicated that HSPA5 and MTPN over-expressed in Glioma samples compared to normal samples." (PMID 34026352, 2021). "HSPA5 and MTPN are possible biomarkers of gliomas suitable for all populations to improve the prognosis of these patients." (PMID 34026352, 2021). "Our study suggests that HSPA5 and MTPN are possible biomarkers of gliomas suitable for all populations to improve the prognosis of these patients." (PMID 34026352, 2021). "It is equally true of the expression of MTPN protein in gliomas." (PMID 34026352, 2021). "Compared with normal brain tissue (0.60 ± 0.28), the expression of mRNA MTPN in WHO II gliomas and WHO III/IV glioma tissues also increased greatly (0.95 ± 0.19,1.01 ± 0.39), and the difference was statistically significant (P < 0.05)." (PMID 34026352, 2021). "Excluding the previously reported prognostic markers of gliomas from this study, the expression of HSPA5 and MTPN were examined by qRT-PCR and immunohistochemical assay." (PMID 34026352, 2021). "By literature search, we excluded the previously reported prognostic biomarkers of gliomas, and obtained two gene signatures (HSPA5 and MTPN) that can predict the prognosis of both white and Asian populations." (PMID 34026352, 2021). "MTPN protein expression in WHO II glioma tissue and WHO III/IV glioma tissue were also significantly higher than normal brain tissue." (PMID 34026352, 2021).
heart failure (2 papers, 2015 to 2020). Inability of the heart to pump blood at an adequate rate to meet tissue metabolic requirements. "The most recent evidence from clinical trials have observed an elevated concentration of plasma myotrophin among patients with heart failure and those after acute myocardial infarction." (PMID 26274321, 2015).
prostate carcinoma (2 papers, 2014 to 2016). A carcinoma that arises from epithelial cells of the prostate gland. "Moreover, it was previously reported that IRES translation could lead to the expression of a novel protein, MPD6, in cancer cells (prostate cancer, chronic myelogenous leukemia) distinct from that coded by the main ORF (myotrophin) and generate a strong immune response." (PMID 27486971, 2016).
type 2 diabetes (2 papers, 2021 to 2023). "Microarray studies have highlighted CAPNS1 as being modulated in membranous nephropathy and in immunoglobulin A nephropathy, while other studies have reported the importance of miR-375 (for which myotrophin MTPN is a target) for glucose homeostasis and as a potential biomarker in type 2 diabetes." (PMID 36769128, 2023). "Additionally, miR-375 was found to be high in serum and pancreatic beta-cells of patients with type 2 diabetes mellitus (T2DM), which directly decreases the gene expression and secretion of insulin through targeting phosphoinositide-dependent kinase-1 (PDK1) and myotrophin, respectively." (PMID 33995938, 2021).
essential hypertension (1 paper, 2015). Hypertension that presents without an identifiable cause. "Possible associations between myotrophin variant and hypertension or left ventricular hypertrophy in the case-control study." (PMID 26274321, 2015).
insulinoma (1 paper, 2019). "MiR-375 is also highly expressed in murine insulinoma MIN6 cells and one study revealed that miR-375 targets the 3’ UTR of the Myotrophin (Mtpn) mRNA." (PMID 32432227, 2019).
invasive breast carcinoma (1 paper, 2020). A carcinoma that infiltrates the breast parenchyma. "Interestingly, MTPN is hypermethylated in DCIS in our study, which could conseqently suppress uncontrolled cell growth and disallow the advancement to invasive breast cancer." (PMID 32051475, 2020).
migraine (1 paper, 2022). "The in-silico analysis showed that the target genes, i.e., HCN3, NAV3, GPR158 for miR-34a-5p and MTPN for miR-375, are involved in trigeminal pain circuit of migraine." (PMID 35682695, 2022).
muscle hypertrophy (1 paper, 2020). "Myotrophin is hypertrophy-inducing factor, which acts in the formal arrangement of actin filaments and promotes cardiac muscle hypertrophy, and was reported as a serum biomarker showing early activation in CHF." (PMID 33256720, 2020).
thyroid disease (1 paper, 2022). "No previous association with thyroid disease has been reported for the remaining five proteins: sialic acid acetylesterase (SIAE), hepatocyte growth factor-regulated tyrosine kinase substrate (HGS), Myotrophin (MTPN), 60S ribosomal protein L24 (RPL24), and Coronin-7 (CORO7)." (PMID 36068205, 2022).
cancer (4 papers, 2013 to 2022). A tumor composed of atypical neoplastic, often pleomorphic cells that invade other tissues. "Although the effect of myotrophin in DCs is not well studied, the expression seems to have an inhibitory effect on NFκB signaling, which in turn has in some cancer studies been seen as a beneficial trait." (PMID 32225009, 2020).
heart (1 paper, 2020). "MTPN was identified originally in a hypertensive rat heart model and has been shown to regulate growth of myocardial cells." (PMID 32722873, 2020).
tumor (1 paper, 2025). "Conversely, PC(16:0/18:1(9Z)), a metabolite significantly downregulated in ARMS, showed negative correlations with ARMS-unique proteins (cyclin-E1, r = −0.71; myotrophin, r = −0.68), which may reflect subtype-specific alterations in lipid metabolism related to tumor progression." (PMID 40710368, 2025).
MTPN also shares sentences with these, for which no sentence is quoted: chronic myelogenous leukemia (1 paper); Hypertension (1); left ventricular hypertrophy (1); lichen (1); membranous nephropathy (1); pancreatic adenocarcinoma (1); psoriasis (1); Stroke (1); thyroid cancer (1); thyroid nodule (1).